EGFR (epidermal growth factor receptor)
Diseases named in the same sentence as EGFR in open-access papers (continued):
Sharing a sentence is not in itself a finding about the gene and the disease.
dermatitis (21 papers, 2015 to 2025). An inflammatory process affecting the skin. "This dermatitis demonstrates the same clinical features as other skin rashes caused by anti‐EGFR antibody, including tiny rashes scattered over the face and eyelids, most of which are symptomless, while a few cause itching and discomfort." (PMID 32017399, 2020). "However, the first-generation TKIs exhibit great potency to bind wild-type EGFR, thus causing numerous side effects such as severe diarrhea and dermatitis." (PMID 35814475, 2022). "It was difficult to distinguish whether the dermatitis was only related to the immunotherapy or was also associated with the increased risk of adverse events due to the PD-1 inhibitor treatment after EGFR-TKI therapy." (PMID 35984168, 2022). "Severe dermatitis acneiform (≥grade 3) was more commonly observed in the group receiving anti-angiogenesis therapy than in the group receiving EGFR-TKI alone." (PMID 35599308, 2022). "Their findings demonstrated that EGFR signaling in keratinocytes regulates key factors involved in skin inflammation, barrier function, and innate host defense, providing insights into the mechanisms underlying EGFRI-induced skin pathologies." (PMID 32252690, 2020). "Activated ERK1/2 has been shown to decrease chemokine mRNA stability and decrease chemokine mRNA expression, suggesting that EGFR-dependent ERK1/2 activity in keratinocytes also participates in homeostatic mechanisms that regulate dermatitis response." (PMID 33113881, 2020). "In dermatitis, amphiregulin has been shown to play a role in wound healing by acting as an epidermal growth factor receptor (EGFR) ligand." (PMID 32153574, 2020). "Patients treated with anti‐EGFR frequently complain of dermatitis, including that of the face and eyelids." (PMID 32017399, 2020). "Furthermore, topical EGFR-inhibitor application in mouse models with contact hypersensitivity, before introducing the contact allergen, led to increased skin inflammation compared to vehicle-treated groups." (PMID 38675137, 2024). "Consequently, EGF treatment, and thus EGFR-signaling stimulation, might be protective in AD as it reduced skin inflammation of AD-like lesions in mice, enhanced skin barrier function, and improved Th1, Th2, and Th17 immune responses." (PMID 38675137, 2024). "Inhibition of EGFR in cuticular cells could aggravate skin inflammation." (PMID 39355840, 2024). "Moreover, EGFR was downregulated at both mRNA and protein levels in dermatitis." (PMID 39355840, 2024). "We used HaCaT cells to analyze the expression of NF‐κB after EGFR‐TKI and adapalene stimulation by western blotting and elucidate the mechanism by which adapalene reduces skin inflammation." (PMID 38379420, 2024). "Pharmacological inhibition of EGFR or its downstream component, extracellular signal-regulated kinase 1/2 (ERK1/2), induce chemokine expression in keratinocytes and skin inflammation." (PMID 31703435, 2019). "Mice lacking epidermal EGFR (EGFRΔep) show a similar phenotype, which is accompanied by chemokine-driven skin inflammation, hair follicle degeneration, decreased host defense, and deficient skin barrier function, as well as early lethality." (PMID 32252690, 2020). "In addition, mouse models lacking epidermal EGFR expression have demonstrated that EGFR signaling in keratinocytes controls skin inflammation and innate immunity, providing an insight into the mechanisms underlying the adverse effects of EGFR inhibitors." (PMID 31703435, 2019).
hepatitis C (21 papers, 2013 to 2025). "The protective miRNAs, hsa-miR-125a-5p and hsa-miR-125b-5p, were identified in this study as targeting 73 genes involved in the HIF-1 signaling pathway, Hepatitis C, and resistance to EGFR tyrosine kinase inhibitors." (PMID 39796139, 2024). "Immunofluorescence for phospho-EGFR was performed on LPS-treated mouse samples and specimens from patients with primary sclerosing cholangitis, primary biliary cirrhosis, hepatitis C, and normal livers." (PMID 25915403, 2015). "EGFR-mediated interferon resistance has been evidenced in the context of hepatitis C." (PMID 27031829, 2016). "KEGG pathway analysis indicated significant enrichment in pathways related to Hepatitis C, HIF-1 signaling pathway, Epstein–Barr virus infection, and EGFR tyrosine kinase inhibitor resistance." (PMID 39796139, 2024). "On the other hand, it has been reported that in hepatitis C virus infection, multiple receptor molecules, including SR-B1, low-density lipoprotein receptor, CD81, claudin-1, occluding, epidermal growth factor receptor, and EphA2 are involved in its process." (PMID 34372540, 2021). "Erlotinib, an epidermal growth factor receptor (EGFR) inhibitor, has been reported to inhibit endocytosis and intracellular trafficking of multiple viruses, including hepatitis C, dengue, and Ebola, exerting broad-spectrum antiviral effects by increasing ACE2 expression." (PMID 34458283, 2021).
influenza (21 papers, 2014 to 2026). An acute viral infection of the respiratory tract, occurring in isolated cases, in epidemics, or in pandemics; it is caused by serologically different strains of viruses (influenzaviruses) designated A, B, and C, has a 3-day incubation period, and usually lasts for 3 to 10 days. "It is also known that respiratory illnesses, including coronavirus and influenza, cause the up-regulation of EGFR to facilitate entry into the host cells." (PMID 33244380, 2020). "Our results show that signaling downstream of EGFR, coagulation pathways, and B-cell down-regulation in the lung are tied to infection severity in highly pathogenic influenza." (PMID 31616667, 2019). "Secondly, despite the validity of PI3K as a potential SOCS5 target, the increased susceptibility of Socs5−/− mice to influenza is due to altered EGFR signaling." (PMID 28195529, 2017). "Although primarily studied in the context of cancer, EGFR has been linked to influenza uptake, to regulation of inflammation following rhinovirus infection, and to prevention of apoptosis in host cells in bacterially infected gastric epithelial cells." (PMID 24586159, 2014). "In this assay, SNs showed reparative abilities, and inhibiting the EGFR signaling pathway by Cetuximab abrogated these reparative abilities, as observed previously with influenza-specific CD8 T cells." (PMID 38226976, 2024). "Gefitinib blockade documented the significance of IL-17 signaling through EGFR in alleviation of lung inflammation in severe influenza." (PMID 37270623, 2023). "Our initial objective is to sort out these discrepancies by investigating the mechanistic link between influenza infection and the EGFR signaling pathway." (PMID 35628375, 2022). "A study further reported that SOCS5 improved control of influenza infection by inhibiting EGFR signaling." (PMID 33758600, 2021). "The role of epidermal growth factor receptor (EGFR) in influenza pathogenesis, one of the bottleneck regulators with corroborating signals across transcript and protein expression data, was tested and validated in additional mouse infection experiments." (PMID 31616667, 2019). "EGFR stimulation has previously been shown to play a role in promoting influenza particle uptake, and EGFR inhibition diminished viral titer in infected mice." (PMID 31616667, 2019). "To validate our findings, we treated mice with the EGFR inhibitor gefitinib during infection with high- and low-path influenza." (PMID 31616667, 2019). "In summary, our study is the first to show that primary human AECs induce IL-8 and GM-CSF through c-Met and EGFR activation and that influenza infection activates c-Met and EGFR in human AECs." (PMID 26033355, 2015). "Influenza-infected mice treated with an EGFR inhibitor have decreased levels of murine IL-8 homolog, MIP-2, and neutrophils in the lungs." (PMID 26033355, 2015). "We conclude that HGF/c-Met and TGF-α/EGFR signaling enhances the innate immune responses by human AECs during influenza infections." (PMID 26033355, 2015). "In a murine influenza model, EGFR inhibition protects mice from influenza infection with a decrease in infectivity by increasing leukocyte migration and IFN-λ and IP-10 secretion." (PMID 26033355, 2015). "Influenza infection stimulated the secretion of IL-8 and GM-CSF by AECs plated on rat-tail collagen through EGFR activation likely by TGF-α released from AECs and through c-Met activated by HGF secreted from lung fibroblasts." (PMID 26033355, 2015). "In this report, we studied cytokine/chemokine induction by recombinant human HGF (rhHGF) and rhTGF-α in human AECs and activation of c-Met and EGFR signaling in AECs during influenza infection." (PMID 26033355, 2015). "An unexpected finding was that EGFR inhibition was less effective at reducing influenza-induced IL-8 secretion in AECs cultured to maintain the alveolar type II cell phenotype." (PMID 26033355, 2015). "EGFR activation has been described as a double-edged sword in influenza infection." (PMID 40496017, 2025).
influenza (continued). "A follow-up validation study in mice confirms the role of EGFR in influenza pathogenicity." (PMID 31616667, 2019). "Thus, EGFR activation is a double-edged sword in influenza infection, promoting viral replication through increased virion uptake or suppression of cytokine production while simultaneously driving tissue maintenance." (PMID 31616667, 2019). "In addition, inhibition of EGFR/PI3K signaling by SOCS5 conferred protection against influenza infection." (PMID 32038638, 2019). "Indeed, EGFR was shown to be important during influenza infection." (PMID 37112680, 2023). "Similarly, this study also raises the possibility that short-term use of EGFR inhibitors in severe influenza may be beneficial, particularly when coupled with direct delivery to the lung; facilitating rapid action, whilst reducing systemic toxicity." (PMID 28195529, 2017). "Therefore, we hypothesized that c-Met and EGFR signaling would induce cytokines/chemokines in primary human AECs during influenza infection." (PMID 26033355, 2015). "Second, c-Met and EGFR regulate multiple functional pathways such as regeneration of the damaged airway epithelium and GM-CSF secretion, which might protect against influenza-induced ARDS." (PMID 26033355, 2015). "Network pharmacology identified genistein and daidzein as key bioactive constituents targeting hub proteins TNF, AKT1, EGFR, SRC, and MMP9, which mediate pathological process in influenza." (PMID 41957261, 2026). "In this study, we are the first to link the anti-influenza activity of AG1478 with GBF1, another non-EGFR target." (PMID 35628375, 2022). "In the present study, we serendipitously found that a small-molecule inhibitor (AG1478), previously used for epidermal growth factor receptor (EGFR) inhibition, demonstrated a potent activity against influenza both in vitro and in vivo." (PMID 35628375, 2022). "For example, the EGFR inhibitor, AG1478, inhibits basal wound closure in human bronchial epithelial cells, and anti-HGF antibody added to mouse lung explants after influenza infection reduces alveolar epithelial regeneration." (PMID 26033355, 2015). "IL-17 signaling through the non-canonical IL-17 receptor EGFR activates the scaffold protein TRAF4 more than TRAF6 during alleviation of lung inflammation in severe influenza." (PMID 37270623, 2023). "Epidermal growth factor receptor has previously been shown to play a role in influenza infection but has not been tied to pathogenicity." (PMID 31616667, 2019). "We demonstrate that EGFR is important during influenza infection, but the role it plays changes for lethal versus non-lethal infections." (PMID 31616667, 2019). "As observed, Influenza induces IL-8 and granulocyte–macrophage colony-stimulating factor (GM-CSF) secretion by human alveolar epithelial cells through recombinant human Hepatocyte growth factor (HGF)/c-Met and TGF-α/ epidermal growth factor receptor (EGFR) signaling." (PMID 40164948, 2025). "Our results suggest that viral neuraminidase-activated TGF-β of the Th1 cells guides the Th17 evolution, and IL-17 signaling through the non-canonical IL-17 receptor EGFR activates the scaffold protein TRAF4 more than TRAF6 during alleviation of lung inflammation in severe influenza." (PMID 37270623, 2023). "Interestingly, and also surprisingly, EGFR per se did not have any effect on influenza infection in our study; rather, the off-target effect of an EGFR inhibitor, AG1478, led to an exciting discovery of a novel anti-influenza pathway." (PMID 35628375, 2022).
osteoporosis (21 papers, 2011 to 2025). A condition of reduced bone mass, with decreased cortical thickness and a decrease in the number and size of the trabeculae of cancellous bone (but normal chemical composition), resulting in increased fracture incidence. "EGFR appears to be an important target protein for inhibiting and intervening in osteoporosis, as it is associated with cell migration, proliferation, and apoptosis." (PMID 40941149, 2025). "We next investigate the role of EGFR overactivation in osteoporosis-induced bone loss." (PMID 40860152, 2025). "The identification of EGFR, ESR1, and SRC as key regulatory hub genes provides valuable insight into the potential molecular mechanisms underlying PPIs-induced osteoporosis." (PMID 40421218, 2025). "We then used molecular docking to screen these peptides for their potential binding affinity to key osteoporosis-related receptors, including Integrins α5β1, Integrins αvβ3, and Epidermal Growth Factor Receptor (EGFR)." (PMID 41003325, 2025). "The epidermal growth factor receptor (EGFR), as an important target protein for inhibiting and intervening in osteoporosis, is associated with cell migration, proliferation, and apoptosis." (PMID 40941149, 2025). "As a result, significant efforts have been devoted to developing high-affinity EGFR-active compounds for the treatment and intervention of osteoporosis." (PMID 40941149, 2025). "Our findings suggest that nitrate enhances the osteogenic differentiation potential of BMSCs by regulating EGFR and mTOR signaling pathways, thereby preventing the osteoporosis." (PMID 38562945, 2024). "The present study showed that salivary nitrate promotes the proliferation and osteogenic differentiation of BMSCs through the EGFR and mTOR signaling pathways, thereby preventing osteoporosis." (PMID 38562945, 2024). "Taken together, these results suggest a novel mechanism for the therapeutic effect of PTH on osteoporosis and an important role of EGFR signaling in mediating PTH's anabolic actions on bone." (PMID 23300521, 2012). "In conclusion, our study demonstrates that osteoblastic EGFR signaling primarily plays an anabolic role in bone metabolism, implying its potential role in osteoporosis." (PMID 21542005, 2011). "Furthermore, we utilized proteomics to identify three key osteoporosis targets (Integrins α5β1, Integrins αvβ3, and EGFR)." (PMID 41003325, 2025). "In this case, we expect Cav-1/EGFR signaling pathway may be another potential anti-osteoporosis therapeutic target." (PMID 37868048, 2023). "As a genetic gene that affects bone mineral density, BICC1 may be a new target for clinical treatment of senile osteoporosis by influencing osteogenic differentiation of BMSCs through EGFR-related signaling." (PMID 35756494, 2022). "FOXO1, BMP4, WNT1, and EGFR in Cluster 2 are related to osteoporosis." (PMID 34777562, 2021). "Furthermore, 36 hub genes of XLGB, such as EGF, EGFR, MTOR, MAPK14 and NFKB1, were considered potential therapeutic targets, suggesting the underlying mechanisms of XLGB acting on osteoporosis." (PMID 32620113, 2020). "It seems that the inhibition of miR-7 targeting the epidermal growth factor receptor (EGFR) may inhibit the development of osteoporosis." (PMID 33126628, 2020). "This study identified EGFR, ESR1, and SRC as key regulatory genes in PPIs-induced osteoporosis, highlighting their roles in bone metabolism." (PMID 40421218, 2025). "We identified EGFR, ESR1, and SRC as key regulatory hub genes, suggesting their crucial roles in bone metabolism and the development of osteoporosis." (PMID 40421218, 2025).
osteoporosis (continued). "After screening the core therapeutic ingredients, a PPI network was constructed to determine core targets; our results showed that AKT1, CASP3, EGFR, ESR1, IGF1, MAPK1, and MAPK14 are important for AB–DA treatment of osteoporosis." (PMID 37849727, 2023). "Collectively, the results reveal that GPR30 is a positive switch for LIG to increase bone formation via regulation of EGFR, and these results provide evidence for the potential of LIG to treat osteoporosis." (PMID 31061445, 2019). "In conclusion, we found that salivary nitrate could enhance the proliferation and osteogenic differentiation potential of BMSCs through the EGFR/AKT/ERK and mTOR/S6K signaling pathways, promote bone formation and prevent osteoporosis." (PMID 38562945, 2024).